CRH (corticotropin releasing hormone)
Diseases named in the same sentence as CRH in open-access papers (continued):
Sharing a sentence is not in itself a finding about the gene and the disease.
endocrine disease (2 papers, 2015 to 2025). "Reversible central adrenal insufficiency (CAI) is a rare endocrine disorder characterized by temporary cortisol deficiency due to reduced adrenocorticotropic hormone (ACTH) or corticotropin-releasing hormone (CRH) secretion from the pituitary or hypothalamus, respectively." (PMID 41446490, 2025). "Regarding novel therapies deriving from endocrine disease concepts, both corticotropin-releasing hormone (CRH) antagonists as well as glucocorticoid receptor (GR) antagonists are being tested clinically for their antidepressive effects." (PMID 26690116, 2015).
intestinal disorder (2 papers, 2017 to 2021). A non-neoplastic or neoplastic disorder that affects the small or large intestine. "Elevated CRH levels damage the mucosal barrier and enhance colonic hyperpermeability, ultimately resulting in stress-related intestinal disorders." (PMID 34873177, 2021). "A full characterization of the role of microbiota and CRH signaling in neonatal intestinal disorders is needed." (PMID 28492284, 2017).
metabolic disease (2 papers, 2022 to 2024). A congenital disorder (due to inherited enzyme abnormality) or acquired (due to failure of a metabolically important organ) disorder resulting from an abnormal metabolic process. "The body’s stress system mediates the stress response, among which, neuroendocrine hormones including corticotropin-releasing hormone in the HPA axis play an important role in the regulation of basal homeostasis and response to threats, and are involved in the pathogenesis of metabolic diseases." (PMID 36348380, 2022).
hematopoietic system disease (1 paper, 2024). "Pathways unique to the PNT2 LMF-treated group were related to corticotropin-releasing hormone signalling pathway, hematopoietic system disease, hemidesmosome assembly, cell junction organisation, and the uptake of dietary cobalamin into enterocytes." (PMID 39336161, 2024).
infectious disease (1 paper, 2025). A disorder directly resulting from the presence and activity of a microbial, viral, or parasitic agent in humans. "In the MULTI group, we identified activation of CRH-related infectious disease response pathways, marked by ABL1 phosphorylation at S183." (PMID 40842862, 2025).
ischaemic heart disease (1 paper, 2020). "For ischaemic heart disease, the CRH group showed a significant IPTW-HR (0.544, 95% CI: 0.317–0.934) compared to the H group." (PMID 31996695, 2020).
urological diseases (1 paper, 2025). "CD24, TOP2A, IQGAP3, UBE2C, and CRH mRNA levels were also significantly higher in patients with NMIBC than in those with hematuria, which may indicate that they could be used as discriminative biomarkers for BCa detection compared to urological diseases." (PMID 40282460, 2025).
CRH also shares sentences with these, for which no sentence is quoted: adenomyosis (5 papers); type 2 diabetes (5); cognitive disorder (4); medullary thyroid carcinoma (4); neurodegenerative disease (4); schizophrenia (4); congenital adrenal hyperplasia (3); hypertriglyceridemia (3); inflammatory skin disorders (3); metabolic syndrome (3); ACTH-dependent Cushing syndrome (2); Adrenal Cushing’s Syndrome (2); agoraphobia (2); alcohol (2); alcohol use disorder (2); amenorrhea (2); amyotrophic lateral sclerosis (2); Cachexia (2); digestive diseases (2); gastric cancer (2); generalized anxiety disorder (2); hyperandrogenemia (2); Hypercholesterolemia (2); hypogonadism (2); immune disorder (2); Miscarriage (2); Parkinson disease (2); perinatal depression (2); small cell lung carcinoma (2); synucleinopathies (2).
A further 101 diseases each share a sentence with CRH in 1 paper.